ERG (ETS transcription factor ERG)
Diseases named in the same sentence as ERG in open-access papers (continued):
Sharing a sentence is not in itself a finding about the gene and the disease.
prostate adenocarcinoma (51 papers, 2010 to 2025). "Recent evidence suggests that ERG overexpression cooperates with PTEN loss in the progression from PIN to prostate adenocarcinoma." (PMID 21829708, 2011). "Therefore, we can support that immunohistochemical homogeneous PTEN loss is predominantly linked to ERG fusions (ERG-positive immunostaining), a mechanism mostly seen in prostate adenocarcinomas of low grade." (PMID 37185705, 2023). "In routine clinical and surgical pathology practice, while some histologic features associated with prostatic adenocarcinoma such as blue mucin production and prominent nucleoli in tumor cells have been shown to demonstrate association with underlying ERG gene rearrangement." (PMID 35513774, 2022). "ERG is overexpressed in approximately half of prostatic adenocarcinomas as a result of a gene fusion with the androgen-driven promoter of the TMPRSS2 gene." (PMID 40141159, 2025). "PAX2 transcriptional silencing in EC is comparable to ERG transcriptional upregulation in prostatic adenocarcinoma, which is strikingly similar to EC." (PMID 40829174, 2025). "TMPRSS2:ERG gene fusion (T:E fusion) in prostate adenocarcinoma (PCa) puts ERG under androgen receptor–regulated (AR-regulated) TMPRSS2 expression." (PMID 41321318, 2025). "TMPRSS2:ERG gene fusion negatively regulates PSMA expression in prostate adenocarcinoma (PCa) cell lines." (PMID 39083067, 2024). "For example, only 21.1% of the recurrent KIAA1549-BRAF fusion in pilocytic astrocytoma and 24.4% of ERG-TMPRSS2 in prostate adenocarcinoma led to neoantigens." (PMID 37461029, 2023). "Using the ‘The Cancer Genome Atlas’ Prostate Adenocarcinoma (TCGA PRAD) database, significant correlations were found between high CPSF4 expression and high-risk genomic abnormalities such as ERG-fusion, ETV1-fusion, and SPOP mutations." (PMID 37629142, 2023). "Researchers have attempted to shed light on the link between PTEN loss and ERG rearrangements with IDPC, as all three phenomena represent important factors in the progression of prostate adenocarcinoma." (PMID 37185705, 2023). "We demonstrated that ERG rearrangement status in prostate adenocarcinoma can be reliably predicted directly from H&E-stained digital slides utilizing a deep learning algorithm with high accuracy." (PMID 35513774, 2022). "Similar to our findings, the TCGA analysis utilizing the dominant focus to classify patients also found that 46% of patients with primary prostate adenocarcinoma undergoing RP can be classified as ERG fusion gene subtype." (PMID 35050902, 2022). "Such an artificial intelligence-based model can eliminate the need for using extra tumor tissue to perform ancillary studies in order to assess for ERG gene rearrangement in prostatic adenocarcinoma." (PMID 35513774, 2022). "We believe that this algorithm can eliminate the need for using extra tumor tissue to perform lengthy and expensive ancillary studies to assess for ERG gene rearrangement in prostatic adenocarcinoma." (PMID 35513774, 2022). "We accordingly sought to develop a deep learning-based algorithm to identify ERG rearrangement status in prostatic adenocarcinoma based on digitized slides of H&E morphology alone." (PMID 35513774, 2022). "A deep learning-based model can successfully predict ERG rearrangement status in the majority of prostatic adenocarcinomas utilizing only H&E-stained digital slides." (PMID 35513774, 2022). "In the present study, we developed a deep learning model to predict ERG rearrangement status in patients with prostatic adenocarcinoma." (PMID 35513774, 2022). "This is of interest because prostate adenocarcinomas from Black men harbor ERG gene rearrangements less frequently than those from White men." (PMID 34191807, 2021). "Pten heterozygous mice overexpressing ERG specifically in the prostate (Pten+/−;Probasin-ERG) developed prostatic adenocarcinoma, whereas Pten+/− mice only showed HGPIN lesions." (PMID 33634124, 2021).
prostate adenocarcinoma (continued). "We performed a co-expression analyses of SFRP1 and ERG in 494 prostate adenocarcinomas samples from the TCGA database; as expected, low positive correlation between SFRP1 and ERG expression was confirmed (Spearman and Pearson." (PMID 32694934, 2020). "Among the vascular markers, CD34 and ERG are the least specific for endothelial cells; the former is expressed in many mesenchymal tumors and the latter is also found in epithelioid sarcomas and prostatic adenocarcinomas." (PMID 38374236, 2025). "In the present study, we analyzed publicly available multiomic data to show that the expression of the TRP channel TRPML2, which is frequently over-expressed in prostate adenocarcinomas and encoded by the MCOLN2 gene, is strongly associated with cases displaying ERG over-expression." (PMID 40332161, 2025). "In this study we developed an AI-based algorithm to establish whether ERG gene arrangement can be determined solely from H&E-based histologic images of patients with prostate adenocarcinoma." (PMID 35513774, 2022). "For each of the RNA-seq data sets corresponding to three adenocarcinoma and 3 non-tumour adjacent prostate tissue samples, we looked for the presence of a fusion gene, TMPRSS2:ERG, which is known to be common in prostate adenocarcinoma, and is a strong prognostic indicator." (PMID 21589938, 2011). "Relation between the status of ERG and H score and IRS of both P4HB and SOX4 in the studied participants with prostatic adenocarcinoma." (PMID 39118797, 2024). "This study aimed to investigate the relationship between renal function parameters and distinctive molecular subtypes of prostate adenocarcinomas, defined by the immunoexpression of the SPINK1, ERG, HOXB13, and TFF3 markers." (PMID 37894380, 2023). "The consortium published the status of ERG, ETV1, ETV4, and FLI1 fusions in the cBioportal database (dataset: Prostate Adenocarcinoma (TCGA, Cell 2015)) for 333 samples." (PMID 37349736, 2023). "Consistent with previous reports, the ERG, TMPRSS2, PTEN, and zinc finger protein family are closely related to the occurrence and progression of prostate adenocarcinoma." (PMID 35547260, 2022). "Approximately half of all prostate adenocarcinomas contain a fusion of an ETS transcription factor with a nearby gene, most typically ETS-related gene (ERG) with transmembrane protease serine-2 (TMPRSS2)." (PMID 25417144, 2014). "Prostate adenocarcinomas developed in all mice transplanted with nontargeting (NT) sgRNA organoids but not in those in which either ERG or Stat3 was deleted." (PMID 40858905, 2025). "The TMPRSS2:ERG gene fusion (T:E fusion) puts ERG under the androgen receptor–regulated (AR-regulated) expression of TMPRSS2, and it is an early truncal alteration found in about half of prostate adenocarcinoma (PCa) cases in men of European ancestry." (PMID 41321318, 2025). "The molecular markers however differ with almost half of patients with SCPC demonstrating ERG (ETS transcription factor) rearrangements (similar to that of prostate adenocarcinoma) compared to an absence of this change in small-cell lung cancer." (PMID 28584167, 2017). "Of the 762 prostatic adenocarcinoma specimens obtained from radical prostatectomy, 613 without neoadjuvant hormone therapy were included in tissue microarrays for quantitatively assessment of ERG and PTEN expression via immunohistochemistry." (PMID 25897494, 2015). "Interestingly, both conventional prostatic adenocarcinoma and SmCC of prostate share ERG gene rearrangement which is absent in SmCC from other body sites." (PMID 25937998, 2015).
acute myeloid leukemia (44 papers, 2008 to 2025). Acute myeloid leukemia (AML) is a group of neoplasms arising from precursor cells committed to the myeloid cell-line differentiation. "We conclude that ERG is a useful additional marker that can be added to the IHC panel in the workup of acute myeloid leukemia." (PMID 38933637, 2024). "They found ERG immunopositivity in 15 of 16 (94%) acute myeloid leukemias/myeloid sarcomas, including four out of five (80%) CD34-negative/CD117-negative acute myeloid leukemias/myeloid sarcomas." (PMID 38933637, 2024). "These acetylation sites have been demonstrated to play a key role regulating ERG function in Acute Myeloid Leukemia." (PMID 34314419, 2021). "In acute myeloid leukaemia (AML), duplication of ERG is significantly related with higher levels of expression and lower overall survival while high ERG expression has been reported as a poor risk indicator in T-cell acute lymphoblastic leukaemia (T-ALL)." (PMID 33007870, 2020). "Aberrant expression of full-length ERG protein has been found in acute myeloid leukemia and acute T-lymphoblastic leukemia." (PMID 27335598, 2016). "High expression of ERG is a poor prognostic indicator in both acute myeloid leukaemia and acute lymphoid leukaemia and increased ERG mRNA expression has been observed in acute myeloid leukaemia patients with complex karyotypes and abnormal chromosome 21." (PMID 27208692, 2016). "BAALC seems to be relevant, not only for differentiating acute myeloid leukemia but also for prognosis in adult T-ALL; high BAALC and ERG expressions are associated with a high risk of relapse and inferior survival." (PMID 22348024, 2012). "Aberrant expression of full-length ERG protein has been found in acute myeloid leukaemia and acute T-lymphoblastic leukaemia." (PMID 22140532, 2011). "Therefore, we considered that isolated gastric MS patient had transformed into acute myeloid leukemia (AML) accompanied by TLS/ERG gene fusion and complex karyotypic abnormalities." (PMID 35623083, 2022). "Furthermore, increased expression of ERG is indicative of poor prognosis of acute lymphoblastic leukemia and cytogenetically normal acute myeloid leukemia." (PMID 35627314, 2022). "In acute myeloid leukemia, ERG expression is high and predicts adverse clinical outcome." (PMID 30237984, 2018). "In summary, ERG is an IHC stain that could help confirm the diagnosis of acute myeloid leukemia." (PMID 38933637, 2024). "In acute myeloid leukemia (AML), a small subset of patients have t(16:21) ERG:FUS fusion, which was first identified in 1994 as a driver of leukemogenesis." (PMID 38933637, 2024). "Aim was to detect Brain and Acute Leukemia, Cytoplasmic (BAALC) and ETS-related gene (ERG) expression in patients with acute myeloid leukemia (AML) as well as to study their biologic and prognostic impact on the disease outcome and survival." (PMID 27335598, 2016). "For example, high expression of the Ets family transcription factor ERG, which is down-regulated after MLL fusion knock-down, is associated with a poor clinical outcome in both acute myeloid leukemia (AML) and T-cell acute lymphoblastic leukemia (T-ALL)." (PMID 25793396, 2015). "ERG was previously identified as one of the LSD1 target genes in HEL and other cell lines of acute myeloid leukemia and myelodysplastic syndromes." (PMID 29765516, 2018). "In the present study, we applied RNA-Seq methodology to an acute myeloid leukemia with a rather complex karyotype and identified a cryptic FUS/ERG fusion gene." (PMID 24068373, 2013). "The upregulated expression of ERG and MYCN, which are important transcription factors that are reported to be positively related to poor clinical outcomes in patients with acute myeloid leukaemia and acute lymphocytic leukaemia, seemed to induce the LSC accumulation mediated by SETD2 deficiency." (PMID 31054182, 2019).
acute myeloid leukemia (continued). "While we are investigating the interaction between BRD4 with wild-type and PCa-associated variants and its role in PCa cell invasion, it has been shown recently that wild-type ERG is acetylated by p300 and interacts with BRD4 to initiate gene transcription in acute myeloid leukemia (AML)." (PMID 27223260, 2016). "Similarly, in acute myeloid leukemia, BRD4 has been shown to co-localize and synergistically interact with hematopoietic TFs (including PU.1, FLI1, ERG, C/EBPα, C/EBPβ, and MYB) combined with lysine acetyltransferase p300/CBP to support specific transcriptional circuits in this disease." (PMID 37446009, 2023).
angiosarcoma (30 papers, 2015 to 2026). A malignant tumor arising from the endothelial cells of the blood vessels. "Although EHE expresses similar molecular markers to angiosarcoma (CD31, CD34, and ERG), angiosarcoma differs greatly from EHE in terms of light microscopy morphology and often exhibits MYC amplification without CAMTA1/TFE3 expression." (PMID 40896782, 2025). "Among malignant tumors, angiosarcomas exhibit aggressive hematogenous dissemination linked to their vascular nature and endothelial marker expression (CD31, CD34, ERG)." (PMID 40427120, 2025). "The endothelial markers CD31, CD34, and ERG will be positive in pyogenic granuloma, hemangioma, vascular malformation, Kaposi sarcoma, and angiosarcoma." (PMID 40895846, 2025). "Angiosarcomas usually express vascular and endothelial markers, including ERG, CD31, CD34, and factor VIII, with CD31 being the most sensitive." (PMID 39958141, 2025). "CD31 expression, used together with CD34 and ERG, is the gold standard for identifying endothelial differentiation in angiosarcoma." (PMID 35049205, 2021). "Pathologic examination confirmed an infiltrative tumor composed of vascular channels delineated by atypical endothelial cells expressing the vascular markers CD31 and ERG, consistent with the diagnosis of angiosarcoma." (PMID 26474454, 2015). "Angiosarcoma is characterized by endothelial markers such as CD 34, CD 31, ERG and factor VIII." (PMID 40583981, 2025). "Our findings indicate that the presence of strong and diffuse TRPS1 expression may lean towards a diagnosis of AFX over angiosarcoma or melanoma, provided it is supported by other commonly used discriminatory immunohistochemical markers like ERG and SOX10." (PMID 39051323, 2024). "Immunohistochemistry showed that myogenin was negative, which may exclude rhabdomyosarcoma, while CD31 and ERG were strongly stained, suggesting Angiosarcoma." (PMID 39142183, 2024). "Immunohistochemistry was performed to validate the expression of ERG (ETS-related gene), a marker used in the human clinic to confirm angiosarcoma." (PMID 41009669, 2025). "Histopathologic confirmation remained the gold standard, with strong positivity for CD31, ERG and CD34 supporting the diagnosis of angiosarcoma." (PMID 40900681, 2025). "Angiosarcomas express endothelial markers, with strong, membranous CD31 staining and nuclear ERG (ETS-related gene) immunoexpression noted." (PMID 41040778, 2025). "Among these, ERG and CD31 exhibit high sensitivity and specificity, with the sensitivity for angiosarcoma approaching 100%." (PMID 39465747, 2024). "Histologic evaluation of the polyps was indicative of angiosarcoma, and the diagnosis was eventually confirmed by immunohistochemical analysis with positive CD31, ERG, and FLI1 stains." (PMID 34150400, 2021). "The tumor cells were negative for desmin, HHF35, HMB45, Melan A, MITF, c-kit, DOG1, cytokeratin AE1/AE3, h-caldesmon, STAT6, CD68, CD31, Factor 8, and ERG, making diagnoses of PEComa, GIST, SFT, and angiosarcoma unlikely." (PMID 34797454, 2021). "Further, immunohistochemical staining of CD34 and ERG, markers of vascular endothelium, distinguishes CRDD from angiosarcoma." (PMID 33354400, 2021). "All formed tumours and histological examination confirmed that these were angiosarcomas expressing both CD31 and ERG." (PMID 31221668, 2019). "Considering the current hypothesis that angiosarcomas originate from blood vessel and lymphatic endothelial cells, the expression of endothelial markers such as FLI1, ERG, CD31, and CD34 becomes pivotal." (PMID 38902365, 2025). "Histologically, angiosarcoma is characterized by spindled, polygonal, epithelioid, and primitive round cells, with expression of both vascular and endothelial antigens on immunohistochemistry, including Factor-VIII, CD31, CD34, and ERG." (PMID 39958141, 2025).
angiosarcoma (continued). "Thus, combinations of one or more of these vascular markers [CD31, CD34, ERG, and FLI1], along with other immunomarkers are required for prompt and accurate diagnosis of angiosarcoma." (PMID 39845895, 2024). "Negative expression of common endothelial vascular markers such as ERG (n = 1), CD34 (n = 16), CD31 (n = 15), and factor VIII-related antigen (n = 10) help confirm that the tumor is epithelial in origin, which aids in ruling out angiosarcoma." (PMID 39199675, 2024). "Histopathological analysis revealed positivity for vascular endothelial markers (CD31, ERG, factor VIII) and absence of MDM2 expression, confirming the diagnosis of angiosarcoma." (PMID 42131296, 2026). "Although there is no pathognomonic immunohistopathological profile, angiosarcomas stain positive for at least one of the following endothelial cell markers: CD34, CD31, ERG, FLI1, and factor VIII-related antigen." (PMID 40255814, 2025). "One of 13 tumors (case 12) showed weak expression of ERG (justifying consideration of solid epithelioid angiosarcoma by the referring pathologist), but it was negative for CD31 and lacked the homogeneous ERG expression characteristic of angiosarcoma." (PMID 33506327, 2021). "The IHC panel confirms that both presence of endothelial markers (CD31 and ERG) and lack of TFE3 and CAMTA have high specificity and sensibility for the diagnosis of angiosarcoma of bone, with focal expression of cytokeratin AE1/AE3 in 9% of the cases." (PMID 32616718, 2020). "However, biopsy results that are positive with IHK CD31, ERG, and negative with IHK AE1, CAMTA1, and TFE can confirm the diagnosis of angiosarcoma." (PMID 39142183, 2024).